POC1B (POC1 centriolar protein B)
Description:
Plays an important role in centriole assembly and/or stability and ciliogenesis. Involved in early steps of centriole duplication, as well as in the later steps of centriole length control. Acts in concert with POC1A to ensure centriole integrity and proper mitotic spindle formation. Required for primary cilia formation, ciliary length and also cell proliferation. Required for retinal integrity. Acts as a positive regulator of centriole elongation.
Synonyms: WDR51B; TUWD12; FLJ14923; POC1B-DUSP6; CORD20; PIX1
Tractability: PROTAC: ubiquitination databases record sites on it; its protein half-life has been measured.
Gene: Protein-coding gene on chromosome 12 (89,419,718 to 89,526,135, reverse strand). Ensembl gene ENSG00000139323.
Subcellular location: Cytoplasm, cytoskeleton, microtubule organizing center, centrosome; Cytoplasm, cytoskeleton, microtubule organizing center, centrosome, centriole; Cytoplasm, cytoskeleton, cilium basal body; Cytoplasm, cytoskeleton, spindle pole
Subcellular location (Human Protein Atlas): Cytosol; Flagellar centriole; Nucleoplasm
Gene Ontology:
Molecular function: protein binding
Biological process: cell population proliferation; centriole replication; cilium assembly; positive regulation of centriole elongation; retina homeostasis; microtubule-based process; multicellular organismal-level homeostasis
Cellular component: centriole; centrosome; ciliary basal body; spindle pole
Genetic constraint (gnomAD): Loss-of-function variants: 28 observed, 39.69 expected, observed/expected ratio (o/e) 0.71, 90% interval 0.52 to 0.97. The upper end of that interval is the gene's LOEUF score, 0.97, which puts it in group 4 of 6, group 1 being the genes least tolerant of losing a copy. Missense variants: 439 observed, 457.72 expected, observed/expected ratio (o/e) 0.96, 90% interval 0.89 to 1.04. Synonymous variants: 142 observed, 154.36 expected, observed/expected ratio (o/e) 0.92, 90% interval 0.8 to 1.06.
Gene-disease validity (ClinGen):
ClinGen rates the evidence that POC1B causes each of these diseases.
cone-rod dystrophy 20 (autosomal recessive): Definitive.
Homologues: Orthologues: chimpanzee POC1B (99% identical), macaque POC1B (99% identical), rabbit POC1B (91% identical), pig POC1B (90% identical), dog POC1B (90% identical), guinea pig POC1B (85% identical), mouse Poc1b (82% identical), rat Poc1b (81% identical), tropical clawed frog poc1b (57% identical). Paralogues in human: POC1A (49% identical), WDR17 (24% identical), TEP1 (21% identical), WDR5B (19% identical), WDR7 (19% identical), WDR5 (18% identical), SNRNP40 (18% identical), AHI1 (17% identical), PAFAH1B1 (17% identical), WDR62 (17% identical), WDR27 (16% identical), WDR75 (16% identical), and 14 more.
Diseases named in the same sentence as POC1B in open-access papers:
POC1B is named in the same sentence as 34 diseases in open-access papers, as found by Europe PMC text mining. Sharing a sentence is not in itself a finding about the gene and the disease. The quoted sentences say what the papers report.
Cone rod dystrophy (6 papers, 2014 to 2025). "POC1B is critical for the photoreceptor connecting cilium and POC1B mutations cause cone-rod dystrophy." (PMID 37691820, 2023).
ciliopathy (5 papers, 2014 to 2025). A genetic disorder of the cellular cilia or the cilia anchoring structures, the basal bodies, or of ciliary function. "Human mutations of either paralog, POC1A or POC1B, cause ciliopathy-like pathologies." (PMID 30741631, 2019). "Notably, human ciliopathy mutations in POC1A or POC1B map to the WD40 repeats." (PMID 30741631, 2019). "Because FAM161A was found to be a retinal-ciliopathy-associated protein, the decreased interaction we observed with this retina-specific protein might induce degeneration of rod photoreceptors as a result of POC1B mutations in individuals with CRD." (PMID 25018096, 2014). "Depletion studies show that POC1B, unlike POC1A, is necessary for ciliogenesis, and typical ciliopathy-associated developmental defects (e.g., curved body axis, kidney cysts, and laterality defects) were described in poc1b morphant zebrafish." (PMID 25018096, 2014). "Another hypothesis involves the role of POC1B in ciliopathies." (PMID 41293231, 2025).
Retinal dystrophy (3 papers, 2023 to 2025). Retinal dystrophy is an abnormality of the retina associated with a hereditary process. "In contrast to our cohort, which showed progressive, moderate to severe vision loss, a Japanese patient with the POC1B-related retinal dystrophy retained good acuity until his 60s, with mild changes on fundal examination, OCT, and ffERG." (PMID 41293231, 2025). "The parafoveal hyperpigmented ring observed in Proband A resembles bull's-eye maculopathy (BEM), often seen in inherited retinal dystrophies such as those caused by POC1B, ABCA4, CRX, and GUCY2D mutations." (PMID 41293231, 2025). "Finally, the presence of optic disc swelling in these cases may be linked to POC1B mutations, the underlying retinal dystrophy, or an unrelated etiology." (PMID 41293231, 2025).
achromatopsia (2 papers, 2020 to 2021). Achromatopsia (ACHM) is a rare autosomal recessive retinal disorder characterized by color blindness, nystagmus, photophobia, and severely reduced visual acuity due to the absence or impairment of cone function. "Due to the very slow progression of the disease combined with normal fundus appearance, decreased visual acuity and photophobia, patients harboring pathogenic variants in POC1B are frequently misdiagnosed with achromatopsia." (PMID 34065499, 2021).
retinal ciliopathies (2 papers, 2014 to 2015). "Homozygotes for the p.Arg106Pro mutation in POC1B have severe, syndromic retinal ciliopathy with defects in kidney and cerebellar function." (PMID 26496357, 2015).
teratospermia (2 papers, 2021 to 2022). "Interestingly, POC1B (aka WDR51B) mRNA is downregulated tenfold in sperm with abnormal morphology (i.e., teratozoospermia)." (PMID 35640396, 2022). "P22p, who has a semen phenotype of teratospermia, had low DC POC1B and high Ax POC1B." (PMID 33968935, 2021).
infertile (1 paper, 2022). "The range differences in fertile men are like those of infertile men with eumorphic sperm (tubulin: 8%, 9%, and 12%; POC1B: 14%, 21%, and 20%; P = 0.25 and 0.06." (PMID 35640396, 2022). "Hence, the objective of this analysis was to test if acetylated tubulin, tubulin, and POC1B, can identify centriolar anomalies in unexplained infertility samples." (PMID 35640396, 2022).
Obesity (1 paper, 2013). Accumulation of substantial excess body fat. "The rest of the candidates, C2orf15, DENND1B, MRPL30, POC1B, RP4-655J12.3, TMBIM4, BMP2 K, CSRNP2, NCKAP5L, TOMM5, and BAP1, may be novel genes related to T2DM or obesity." (PMID 24455749, 2013).
occult macular dystrophy (1 paper, 2021). "Another misinterpreted diagnosis of POC1B-associated retinopathy is occult macular dystrophy, as was also originally suspected in our case MDS438." (PMID 34065499, 2021).
retinal degeneration (1 paper, 2021). Degeneration of the retina. "As mutations in POC1B are a rare cause of inherited retinal degeneration, we aimed to characterize three patients with biallelic POC1B variants at the clinical and molecular level." (PMID 34065499, 2021). "Mutations in POC1B are a rare cause of inherited retinal degeneration." (PMID 34065499, 2021).
retinopathy (3 papers, 2018 to 2025). "Our cases expand the phenotypic spectrum of POC1B-associated retinopathies and highlight the importance of considering optic disc swelling as a possible, albeit rare, feature in COD/CORD." (PMID 41293231, 2025). "The retinopathy caused by recessive biallelic mutations in POC1B shows several phenotypic characteristics." (PMID 34065499, 2021). "Based on these observations, POC1B-associated retinopathy is mostly classified as either CD or CORD." (PMID 34065499, 2021). "A broad range of age at onset in POC1B-associated retinopathy has also been reported previously." (PMID 34065499, 2021). "In addition, the multimodal evaluations of three cases with POC1B retinopathy expand the current clinical knowledge about this very rare phenotype of POC1B-associated slowly progressive CD or CORD." (PMID 34065499, 2021).
POC1B also shares sentences with these, for which no sentence is quoted: cone dystrophy (2 papers); Hypertension (2); Joubert syndrome (2); Leber congenital amaurosis (2); autosomal recessive cone rod dystrophy (1); Blindness (1); Bull's eye maculopathy (1); Chudley-McCullough syndrome (1); diabetes (1); hypotrichosis (1); Kidney Cyst (1); kidney disease (1); macular degeneration (1); Oguchi disease (1); onychodysplasia (1); papilledema (1); Pigmentary retinopathy (1); pituitary hormone deficiency (1); Retinal (1); retinal diseases (1); retinitis pigmentosa (1); SOFT syndrome (1); tumor (1).